PLP1 (proteolipid protein 1)
Description:
This is the major myelin protein from the central nervous system. It plays an important role in the formation or maintenance of the multilamellar structure of myelin.
Synonyms: PLP; GPM6C; HLD1; MMPL; PLP/DM20; PMD; SPG2
Tractability: Antibody: UniProt places it where antibodies can reach, with high confidence; its Gene Ontology location is reachable by antibodies, with high confidence; UniProt predicts a signal peptide or a membrane-spanning region.
Gene: Protein-coding gene on chromosome X (103,769,047 to 103,792,677, forward strand). Ensembl gene ENSG00000123560.
Subcellular location: Cell membrane; Myelin membrane
Gene Ontology:
Molecular function: protein binding; structural constituent of myelin sheath; structural molecule activity
Biological process: substantia nigra development; axon development; axon ensheathment; central nervous system myelination; chemical synaptic transmission
Cellular component: plasma membrane; myelin sheath; membrane; synapse
Gene-disease validity (ClinGen):
ClinGen rates the evidence that PLP1 causes each of these diseases.
Pelizaeus-Merzbacher spectrum disorder (X-linked): Definitive.
Homologues: Orthologues: chimpanzee PLP1 (100% identical), guinea pig PLP1 (100% identical), mouse Plp1 (100% identical), rat Plp1 (100% identical), dog PLP1 (99% identical), pig PLP1 (99% identical), macaque PLP1 (99% identical), rabbit PLP1 (90% identical), tropical clawed frog plp1 (68% identical), zebrafish plp1a (51% identical), zebrafish plp1b (44% identical), Drosophila melanogaster M6 (22% identical), and 1 more. Paralogues in human: GPM6B (47% identical), GPM6A (36% identical).
Diseases named in the same sentence as PLP1 in open-access papers:
PLP1 is named in the same sentence as 135 diseases in open-access papers, as found by Europe PMC text mining. Sharing a sentence is not in itself a finding about the gene and the disease. The quoted sentences say what the papers report.
Pelizaeus-Merzbacher disease (61 papers, 2007 to 2025). "PLP1 is also implicated in Pelizaeus-Merzbacher disease, a leukodystrophy that causes intellectual disability, among other neurological deficits; thus, it has high relevance for human cognition." (PMID 40043106, 2025). "Pelizaeus-Merzbacher disease (PMD) is a pediatric disease caused by mutations in the X-linked myelin gene proteolipid protein (PLP1)." (PMID 38273973, 2023). "This study aimed to characterize the clinical features, developmental milestones, and the natural history of Pelizaeus-Merzbacher disease (PMD) associated with PLP1 gene duplications." (PMID 37636890, 2023). "Pelizaeus-Merzbacher disease is caused by mutations in PLP1, encoding major myelin-resident protein required for myelin sheath assembly." (PMID 35217805, 2022). "An example is Pelizaeus-Merzbacher Disease (PMD) most often caused by duplications in the PLP1 gene that encodes two primary components of myelin." (PMID 32477268, 2020). "For example, the prototypical HLD Pelizaeus-Merzbacher disease results from pathogenic variants in PLP1, a gene encoding a structural myelin protein." (PMID 33633543, 2020). "Pelizaeus-Merzbacher disease is a fatal X-linked leukodystrophy caused by mutations in the PLP1 gene, which is expressed in the CNS by oligodendrocytes." (PMID 32419025, 2020). "In patients with a PLP1 duplication mutation, the most common cause of Pelizaeus-Merzbacher disease, the pathology is poorly defined because of a paucity of autopsy material." (PMID 32419025, 2020). "Pelizaeus-Merzbacher disease (PMD) is caused by point mutations or copy number changes in the proteolipid protein 1 gene (PLP1)." (PMID 31110947, 2019). "Pelizaeus Merzbacher Disease is a rare X-linked central nervous system disease involving the proteolipid protein 1 gene." (PMID 31065145, 2018). "We detected a novel pathogenic PLP1 missense mutation c.251C > A (p.Ala84Asp) allowing us to make a diagnosis of Pelizaeus-Merzbacher Disease for this family." (PMID 29486744, 2018). "Duplications and deletions affecting the PLP1 gene causing Pelizaeus-Merzbacher disease (OMIM #312080) are also associated with a specific LCR (LCR-PMD A/B pair) within a 3-Mb region flanking the gene in which a multitude of LCRs are located." (PMID 27663310, 2016). "The Xq22.2 region harbors PLP1 causative for Pelizaeus-Merzbacher disease characterized by cognitive impairment, severe spasticity, hypotonia, nystagmus and ataxia." (PMID 27506666, 2016). "Among these genes, PLP1 mutations have been previously shown to be associated with the neurological disorder Pelizaeus-Merzbacher disease (MIM 312080) characterized by intellectual disability, nystagmus, ataxia, spasticity, and microcephaly." (PMID 27506666, 2016). "SLC16A2 mutation screening has therefore to be considered in males presenting with features of Pelizaeus-Merzbacher disease or X-linked spastic paraplegia, an allelic condition, once PLP1 mutations have been excluded." (PMID 24665922, 2014). "A fourth gene, Plp1, is implicated in Spastic paraplegia-2 and Pelizaeus-Merzbacher diseases, which are disorders closely related to ataxia." (PMID 23028291, 2012). "PLP1 mutations are the most common, causative for Pelizaeus-Merzbacher disease." (PMID 35217805, 2022). "Importantly, different types of mutations in PLP1 gene leads to demyelination in a group of disorders known as hypomyelinating leukodystrophies (Pelizaeus-Merzbacher diseases), while PLP overexpression causes oligodendrocytes death." (PMID 35132494, 2022). "The essential role played by the myelin proteolipid protein (PLP) in normal functioning of the central nervous system (CNS) is illustrated by the fact that mutations in PLP1 result in either Pelizaeus-Merzbacher disease (PMD) or spastic paraplegia type 2 (SPG2), which are X-linked leukodystrophies." (PMID 36713780, 2022).
Pelizaeus-Merzbacher disease (continued). "Of note, absent or reduced myelination in the context of an evolving spastic paraplegia in males with AHDS may lead to the misdiagnosis of Pelizaeus-Merzbacher disease, a disorder of myelination due to mutations in the PLP1 gene on Xq22." (PMID 24665922, 2014). "Interestingly, duplication of PLP1 is one of the most common causes of demyelination in Pelizaeus-Merzbacher disease." (PMID 24495672, 2014). "WES allowed us to have a conclusive diagnosis identifying a novel missense PLP1 mutation, suggesting a diagnosis of Pelizaeus-Merzbacher Disease (PMD)." (PMID 29486744, 2018). "Pelizaeus-Merzbacher disease (PMD) is neurodegenerative leukodystrophy caused by dysfunction of the proteolipid protein 1 (PLP1) gene on Xq22, which codes for an essential myelin protein." (PMID 25789183, 2015). "For example, Pelizaeus-Merzbacher disease (PMD) is an X-linked recessive neurodegenerative leukodystrophy largely caused by three genetic lesions in the PROTEOLIPID PROTEIN 1 (PLP1) gene: deletions, duplications and missense/nonsense mutations." (PMID 24575297, 2013). "These modifications and approaches generated Pelizaeus-Merzbacher Disease (PMD)-specific human iPSCs from two individuals with varying clinical severity and PLP1 missense mutations." (PMID 39195216, 2024). "Our work supports a disease mechanism for leukodystrophies by which mislocalisation of MAL affects the distribution of PLP1, resulting in a hypomyelination disorder similar to Pelizaeus-Merzbacher disease." (PMID 35217805, 2022). "Our results suggest that mislocalisation of MAL affects the distribution of PLP1, consistent with known pathomechanisms for Pelizaeus-Merzbacher disease." (PMID 35217805, 2022). "In the literature, increased copies in PLP1 gene and subsequently in PLP protein lead to an X-linked inherited demyelinating disorder, that of Pelizaeus-Merzbacher disease (PMD)." (PMID 36478958, 2022). "A family with a history of Pelizaeus-Merzbacher disease (PMD) received prenatal diagnosis of PLP1 gene duplication in a fetus using a single nucleotide polymorphism (SNP) array." (PMID 33429367, 2021). "Pelizaeus-Merzbacher disease (PMD) is an X-linked hypomyelinating leukodystrophy caused by mutation, deletion or duplication of the PLP1 gene." (PMID 33763430, 2021). "Previous studies revealed that overexpression of PLP1 enhanced the accumulation of lipids in the myelin sheath, thereby promoting the progression of diseases in the central nervous system, such as Pelizaeus-Merzbacher disease." (PMID 34516348, 2021). "The transcriptional dynamics in Schwann cell differentiation resolved by scRNA-seq include genes associated with congenital demyelinating diseases such as Pmp22 (Charcot Marie Tooth and Deafness Syndrome) and Plp1 (Pelizaeus-Merzbacher disease)." (PMID 34003106, 2021). "Among the PLP1-related disorders, Pelizaeus-Merzbacher disease (PMD) is the more severe and best-known condition." (PMID 33450882, 2021). "In the field of HLDs, a recent study has demonstrated that CRISPR-Cas9 mediated germline suppression of Plp1 in the severe jimpy mouse model of Pelizaeus-Merzbacher disease leads to increased myelination and restored lifespan." (PMID 33633543, 2020). "HLD1, also called Pelizaeus-Merzbacher disease (PMD), is associated with various types of mutations (point mutations, deletion, and multiplication) of the plp1 gene (OMIN ID." (PMID 32384815, 2020). "Our case highlights the second only known female with Pelizaeus Merzbacher Disease due to deletions of proteolipid protein 1 gene." (PMID 31065145, 2018). "Pelizaeus-Merzbacher disease (PMD; MIM#312080) is a rare X-linked hypomyelinating leukodystrophy related to genomic alterations of the proteolipid protein 1 (PLP1) gene." (PMID 26329556, 2015).
Pelizaeus-Merzbacher disease (continued). "First, we observe innate immune system activation in autopsy specimens from Pelizaeus-Merzbacher disease (PMD) patients and mouse models stemming from PLP1 gene mutations." (PMID 24575297, 2013). "Microduplications encompassing the PLP1 gene have also been reported with a clinical phenotype evocative of Pelizaeus-Merzbacher disease (PMD)." (PMID 19232094, 2009). "This is in line with the findings in studies of deletions of the dystrophin gene in DMD and duplications of PLP1 in Pelizaeus-Merzbacher disease." (PMID 17277737, 2007). "The hypomyelinating phenotype of these patients suggests functional mutations in MCT8 may affect the development of OLs and myelination similar to other severe inherited leukodystrophies such as Pelizaeus-Merzbacher disease (PMD) caused by the duplication of the PLP1 gene." (PMID 31182964, 2019). "Pelizaeus-Merzbacher disease (PMD) is an X-linked genetic disorder in which multiplication, deletion, or missense mutations of the plp1 gene lead to elevated expression of proteolipid protein 1 (PLP1), and subsequently mild to severe dysmyelination-related symptoms." (PMID 26409478, 2016). "Notably, genetic evaluation excluded a differential diagnosis of alternate conditions, including spinal muscular atrophy (SMA), through negative SMN1/SMN2 deletion/duplication analysis, and Pelizaeus-Merzbacher disease, as PLP1 mutation analysis was negative." (PMID 40243727, 2025). "For example, the duplication of plp1 in mice leads to a dysmyelinating phenotype, observed in Pelizaeus-Merzbacher disease (PMD)." (PMID 31182964, 2019). "The archetypical example is Pelizaeus-Merzbacher disease (PMD) (MIM: 312080), an X-linked disease caused by mutations in the PLP1 (MIM: 300401), which codes for proteolipid protein-1, a major component of myelin." (PMID 28575651, 2017). "While her phenotypic features such as cognitive impairment and motor delay show overlap with Pelizaeus-Merzbacher disease (PMD) caused by PLP1 mutations at Xq22.2, this gene is not included in our patient’s microdeletion and is not dysregulated by a position effect." (PMID 27506666, 2016). "For example, an RNA-based therapeutic targeting proteolipid protein 1 (PLP1), the gene defective in Pelizaeus-Merzbacher disease (PMD), has been investigated." (PMID 38769304, 2024). "However, the clinical and radiological findings of the patient were compatible with a severe phenotype of Pelizaeus-Merzbacher disease rather than HEMS, which may be due to undetected abnormal PLP1 splicing." (PMID 33795668, 2021).
leukodystrophy (18 papers, 2013 to 2025). Leukodystrophies are a group of rare, progressive, metabolic, genetic diseases that affect the brain, spinal cord and often the peripheral nerves. "Here we describe a family of Cocker Spaniels with a hypomyelinating leukodystrophy caused by a novel variant in the proteolipid protein 1 (Plp1) gene." (PMID 39969014, 2025). "We describe a prenatal case involving a microarray-detected duplication of PLP1 which causes X-linked Pelizaeus-Merzbacher disease, a progressive hypomyelinating leukodystrophy." (PMID 37560384, 2023). "The importance of transmembrane domains in genetic disease has been demonstrated in the context of Pelizeus-Merzbacher disease, an early-onset leukodystrophy defined by mutations of the PLP1 gene." (PMID 37415600, 2023). "PMD is a hypomyelinating leukodystrophy caused by mutations in the PLP1 gene, encoding an abundant myelin protein." (PMID 35748297, 2022). "PMD is a rare hypomyelinating leukodystrophy, predominantly arising from mutations involving the dosage-sensitive proteolipid protein 1 gene (PLP1, MIM 300401)." (PMID 31818324, 2019). "In humans, mutations in the PLP1 gene including null, point and duplication/triplication changes, cause allelic leukodystrophies with a broad range of clinical severity, from spastic paraplegia type 2 (SPG2) to the connatal forms of PMD." (PMID 30050403, 2018). "Mutations in PLP1 alter myelin formation, and cause a spectrum of disorders with distinct genotype–phenotype correlations and variable severity, most of them belonging to the group of hypomyelinating leukodystrophies." (PMID 33450882, 2021). "In this paper, we present four unreported HEMS patients from three families harboring three novel PLP1 mutations in exon 3B and describe their main clinical, genetic and neuroradiological data, to expand the phenotypic and genotypic spectrum of this rare hypomyelinating leukodystrophy." (PMID 33450882, 2021). "This proves that the PLP1 gene was up-regulated in piglets that experienced intermittent neonatal MS in this experiment, resulting in leukodystrophy and affecting cognitive function." (PMID 37645701, 2023). "The duplication as well as more than 60 mutations found in the PLP1 gene lead to PMD, a lethal leukodystrophy." (PMID 35829923, 2022). "Our results suggest that mislocalisation of MAL affects PLP1 distribution, consistent with known pathomechanisms for hypomyelinating leukodystrophies." (PMID 35217805, 2022). "We present a missense variant in MAL as the likely cause of hypomyelinating leukodystrophy, resulting in ER mislocalization of mutant MAL leading to possible defects in PLP1 trafficking." (PMID 35217805, 2022). "Trio-based WES was performed for 20 unresolved HLDs families after genetic tests for the PLP1 duplication and a panel of 115 known leukodystrophy-related genes." (PMID 33597727, 2021). "In our HLDs cohort in China, out of 205 cases, genetic tests for the PLP1 duplication and a panel of 115 known leukodystrophy-related genes diagnostically solved 155 cases (~75%)." (PMID 33597727, 2021). "In our HLDs cohort, genetic tests including MLPA targeted for the PLP1 duplication and a panel of 115 known leukodystrophy-related genes diagnostically solved ~75% of cases (155/205)." (PMID 33597727, 2021).
multiple sclerosis (13 papers, 2013 to 2025). A progressive autoimmune disorder affecting the central nervous system resulting in demyelination. "Plp1 dysregulation has also been implicated in other neurodegenerative disorders such as multiple sclerosis and elevation of Plp1 leads to widespread microglial reactivity and neuroinflammation." (PMID 35897073, 2022). "In this regard, missense mutations in PLP1 have been identified in patients exhibiting clinical symptoms consistent with a diagnosis of multiple sclerosis." (PMID 36672024, 2022). "PLP1 encodes the most abundant myelin protein which is a main target of autoreactive T cells in multiple sclerosis (MS) and is detected in cervical LNs of MS patients." (PMID 32784936, 2020). "Nevertheless, numerous case reports have shown individuals with PLP1 missense point mutations which also presented clinical symptoms and indications that were consistent with the diagnostic criteria of multiple sclerosis (MS), a disabling disease of the brain and spinal cord with no current cure." (PMID 36672024, 2022). "However, several case studies have identified patients with missense point mutations in PLP1 and clinical symptoms and signs compatible with a diagnosis of multiple sclerosis (MS)." (PMID 30314286, 2018). "Interestingly, PLP1 mutations have also been linked to multiple sclerosis (MS), where they appear to facilitate pathogenic immune responses and lymphocyte activation, suggesting that genetic and inflammatory mechanisms may converge on common oligodendroglial targets." (PMID 40429767, 2025). "Quantitative RT-PCR analysis demonstrated an ∼1.25-fold higher level of PLP1 gene expression than in a patient with multiple sclerosis." (PMID 32419025, 2020). "Also, proteins encoded by human orthologs of PLP1, MBP, and MOBP are known to be antigens recognized by CD4+ T cells in multiple sclerosis patients." (PMID 36817487, 2023).
Spastic paraplegia type 2 (13 papers, 2011 to 2025). Spastic paraplegia type 2 (SPG2) is an X-linked leukodystrophy characterized primarily by spastic gait and autonomic dysfunction. "Mutations in the PLP1 gene cause the development of a wide continuum spectrum of leukopathies from the most severe form of PMD for whom patients exhibit severe CNS hypomyelination to the relatively mild late-onset type 2 spastic paraplegia, leading to the concept of PLP1-related disorders." (PMID 35885014, 2022). "X-linked dysmyelinating disorders such as Pelizaeus–Merzbacher disease (PMD) or spastic paraplegia type 2 (SPG2) are typically caused by point mutations in PLP1." (PMID 36672024, 2022). "Notably, PLP1 encodes for the major myelin proteolipid protein, that plays a role not only for stabilization and maintenance of myelin sheaths, but also for axonal survival; mutations in this gene cause spastic paraplegia type 2 and Pelizaeus-Merzbacher disease." (PMID 27982123, 2016). "Mutations in the X-linked PLP1-gene (encoding PLP and its smaller isoform DM20) lead to dysmyelinating disease with a broad clinical spectrum, ranging from severe Pelizaeus–Merzbacher disease (PMD) to milder spastic paraplegia type 2 (SPG-2)." (PMID 24431989, 2014). "PLP1, the gene encoding PLP and DM20, is located on the X chromosome; multiple copies of PLP1, deletion of PLP1,or point mutations in PLP1 can lead to the X-linked dysmyelinating disorders, Pelizaeus-Merzbacher disease (PMD), and spastic paraplegia type 2 (SPG2)." (PMID 24312732, 2013).
Ataxia (9 papers, 2011 to 2025). Ataxia refers to impaired coordination of voluntary muscle movement. "During his life, the patient underwent extensive targeted testing for known genes associated with ataxia and spasticity (spastic paraplegias 3A, 4, and 7; spinocerebellar ataxias 1, 2, 3, 6, 7, and 14; FXN‐, APTX‐, SETX‐, PLP1‐, and LCFA‐related disorders)." (PMID 34753215, 2022). "Likewise, PLP1, NKX6-2, and ATP1A3 mutations are linked to spasticity, ataxia, and cognitive deficits." (PMID 41300846, 2025).